CCND3 (cyclin D3)
Diseases named in the same sentence as CCND3 in open-access papers (continued):
Sharing a sentence is not in itself a finding about the gene and the disease.
infection (5 papers, 2016 to 2025). The state of being infected such as from the introduction of a foreign agent such as serum, vaccine, antigenic substance or organism. "Control (NT siRNA-treated) and cyclin D3-deficient cells were infected with A/WSN/33 at an MOI of 0.01 to allow multiple rounds of infection." (PMID 28130444, 2017). "Cells were transduced with lentivirus to deliver wild‐type (WT) cyclin D3 or mutant T283A cyclin D3, before infection with live SARS‐CoV‐2." (PMID 36161661, 2022). "Cells complemented with cyclin D3 WT and T283A showed higher cyclin D3 expression than controls as expected; however, after infection, only WT cyclin D3 was degraded while T283A cyclin D3 protein persisted." (PMID 36161661, 2022). "Infection by influenza A virus triggered redistribution of cyclin D3 from the nucleus to the cytoplasm, followed by its proteasomal degradation." (PMID 28130444, 2017). "We further verified colocalization of cyclin D3 with that of M2 through infection of A/WSN/33 in cyclin D3-expressing cells." (PMID 28130444, 2017). "The only GO term and KEGG pathway commonly over-represented in genes downregulated after both SA treatment and Cmm infection were G1/S transition of the mitotic cell cycle (GO:0000082) and cyclin D3, plant (K14505), respectively, which are related to cell division." (PMID 38434116, 2023). "Collectively, cyclin D3 is expressed in tissues along the natural infection route of IAV." (PMID 28130444, 2017). "Thus, an obvious rescue of cyclin D3 was observed after one round of infection (9 h p.i.)through the use of proteasome inhibitors." (PMID 28130444, 2017). "Validating these unexpected results, a flow cytometry study of markers of proliferation cyclin D3 and Ki67 showed a correlated decrease in protein level in unpurified, minimally disturbed HIV-infected cells compared to uninfected cells starting as early as 48 hours post infection." (PMID 41006834, 2025). "To exclude the possibility that cyclin D3 depletion affects genomic replication, we depleted cyclin D3 in VERO AT2 cells and infected these cells with SARS‐CoV‐2 for 8 h, allowing one round of infection, and for 24 h, allowing multiple (~ 3) rounds of infection." (PMID 36161661, 2022).
myopathy (1 paper, 2022). A disease of the muscle in which the muscle fibers do not function properly. "It has been shown that the increase in GSK3β in DM1 affects the cyclin D3-CUGBP1 pathway, contributing to the DM1 muscle phenotype (myotonia, atrophy, muscle weakness and myopathy) in DM1 mice and muscle weakness, myopathy and anxiety in DMSXL mice." (PMID 36142405, 2022).
CCND3 also shares sentences with these, for which no sentence is quoted: sarcoma (6 papers); medulloblastoma (2); adenosarcoma (1); anaplastic thyroid carcinoma (1); asthma (1); atherosclerosis (1); B-cell acute lymphoblastic leukemia (1); bacterial infection (1); bone sarcoma (1); cardiac hypertrophy (1); cervical cancer (1); cervical squamous cell carcinoma (1); chondrosarcoma (1); dysplastic (1); dysplastic nevi (1); esophageal cancer (1); Fanconi anemia complementation group G (1); fibrosarcoma (1); head-neck cancer (1); hematological cancers (1); Hodgkins lymphoma (1); hypophosphatemia (1); Infertility (1); latent infection (1); liposarcoma (1); lung squamous cell carcinoma (1); Lymphatic Metastasis (1); malignant fibrous histiocytoma (1); malignant mesothelioma (1); malignant peripheral nerve sheath tumor (1).
A further 16 diseases each share a sentence with CCND3 in 1 paper.